HMGCLL1 (3-hydroxy-3-methylglutaryl-CoA lyase like 1)
Description:
Non-mitochondrial 3-hydroxy-3-methylglutaryl-CoA lyase that catalyzes a cation-dependent cleavage of (S)-3-hydroxy-3-methylglutaryl-CoA into acetyl-CoA and acetoacetate, a key step in ketogenesis, the products of which support energy production in nonhepatic animal tissues.
Synonyms: er-cHL; DKFZP434G1411; bA418P12.1; ERCHL
Tractability: Antibody: UniProt places it where antibodies can reach, with medium confidence.
Gene: Protein-coding gene on chromosome 6 (55,434,368 to 55,579,197, reverse strand). Ensembl gene ENSG00000146151.
Subcellular location: Cytoplasm, cytosol; Endoplasmic reticulum membrane
Pathways (Reactome):
Metabolism: Synthesis of Ketone Bodies
Gene Ontology:
Molecular function: hydroxymethylglutaryl-CoA lyase activity; metal ion binding; catalytic activity; oxo-acid-lyase activity
Biological process: ketone body biosynthetic process; L-leucine catabolic process
Cellular component: cytosol; endoplasmic reticulum; endoplasmic reticulum membrane; membrane; perinuclear region of cytoplasm
Genetic constraint (gnomAD): Loss-of-function variants: 18 observed, 20.62 expected, observed/expected ratio (o/e) 0.87, 90% interval 0.6 to 1.29. The upper end of that interval is the gene's LOEUF score, 1.29, which puts it in group 5 of 6, group 1 being the genes least tolerant of losing a copy. Missense variants: 254 observed, 248.93 expected, observed/expected ratio (o/e) 1.02, 90% interval 0.92 to 1.13. Synonymous variants: 86 observed, 89.95 expected, observed/expected ratio (o/e) 0.96, 90% interval 0.8 to 1.14.
Homologues: Orthologues: chimpanzee HMGCLL1 (100% identical), macaque HMGCLL1 (99% identical), dog HMGCLL1 (96% identical), pig HMGCLL1 (95% identical), rabbit HMGCLL1 (95% identical), mouse Hmgcll1 (93% identical), rat Hmgcll1 (92% identical), guinea pig HMGCLL1 (81% identical), tropical clawed frog hmgcll1 (72% identical), zebrafish hmgcll1 (69% identical), Drosophila melanogaster Hmgcl (54% identical), Caenorhabditis elegans Y71G12B.10 (47% identical). Paralogues in human: HMGCL (64% identical).
Diseases named in the same sentence as HMGCLL1 in open-access papers:
HMGCLL1 is named in the same sentence as 10 diseases in open-access papers, as found by Europe PMC text mining. Sharing a sentence is not in itself a finding about the gene and the disease. The quoted sentences say what the papers report.
brain cancer (1 paper, 2017). A primary or metastatic malignant neoplasm affecting the brain. "In addition, HMGCLL1 has been shown to be upregulated in several human cancers such as breast cancer and brain cancer." (PMID 28427185, 2017).
colorectal cancer (1 paper, 2012). A primary or metastatic malignant neoplasm that affects the colon or rectum. "HMGCLL1 has been show to be related to various cancers, such as pancreatic cancers, glioblastoma multiforme, breast and colorectal cancers." (PMID 22496748, 2012).
pancreatic cancers (1 paper, 2012). "HMGCLL1 is one of the genes containing somatic mutations in pancreatic cancer." (PMID 22496748, 2012).
cancer (4 papers, 2012 to 2023). A tumor composed of atypical neoplastic, often pleomorphic cells that invade other tissues. "In contrast, lower expression of the downregulated genes (such as SCARA5, MYOM1, NKAPL, PEG3, USP2, SLC5A7 and HMGCLL1) in various cancers is associated with poor clinical outcomes in cancer." (PMID 28427185, 2017). "Though mutation in HMGCLL1 has been reported to be involved in these cancers, the specific mechanisms underlying remain to be elucidated." (PMID 22496748, 2012). "HMGCLL1 polymorphisms have been reported to be relevant for cancer cell growth and viability." (PMID 38110715, 2023). "We identified consistently upregulated genes (such as E2F1, EZH2, FOXM1, MYBL2, PLK1, TTK, AURKA/B and BUB1) and consistently downregulated genes (such as SCARA5, MYOM1, NKAPL, PEG3, USP2, SLC5A7 and HMGCLL1) across various cancers." (PMID 28427185, 2017). "The role of HMGCLL1 in susceptibility or resistance of cancer cells to chemotherapies has never been extensively investigated." (PMID 30555164, 2019).
HMGCLL1 also shares sentences with these, for which no sentence is quoted: breast carcinoma (1 paper); chronic myeloid leukemia (1); glioblastoma multiforme (1); hepatoma (1); Obesity (1); prostate carcinoma (1).